ENG (endoglin)
Diseases named in the same sentence as ENG in open-access papers (continued):
Sharing a sentence is not in itself a finding about the gene and the disease.
Ewing sarcoma (7 papers, 2012 to 2022). A small round cell tumor that lacks morphologic, immunohistochemical, and electron microscopic evidence of neuroectodermal differentiation. "Endoglin, coreceptor of the TGFβ family, is an interesting and perspective target for Ewing' sarcoma as its high expression is associated with poor prognosis of the disease." (PMID 32317857, 2020). "Our group has shown that treatment with anti-ENG ADCs strongly impaired tumor growth in Ewing sarcoma cell line-derived xenografts and patient-derived xenografts." (PMID 33804796, 2021). "Notably, the expression of ENG was heterogeneous in human Ewing sarcoma neoplastic clinical samples, which stresses the need for a good screening procedure (ENG expression) in a clinical context." (PMID 33804796, 2021). "Another piece of evidence for MMP14 activity in Ewing sarcoma is that the same cells expressing MMP14 protein also present soluble Endoglin, a membrane coreceptor of the TGFβ family, which is cleaved by MMP14 and associates with poor prognosis in Ewing sarcoma." (PMID 31466240, 2019). "We recently reported that anti-ENG drug conjugates are a promising option for the treatment of Ewing sarcoma (ES)." (PMID 35955799, 2022). "Our previous work demonstrated potent preclinical activity of first-in-class anti-ENG antibody-drug conjugates as a nascent strategy to eradicate Ewing sarcoma (ES), a devastating rare bone/soft tissue cancer with a putative MSC origin." (PMID 35955799, 2022). "Endoglin (CD105), a TGF-β co-receptor, has been shown to induce VM formation and neo-angiogenesis in Ewing’s sarcoma." (PMID 35747793, 2022). "Thus, monoclonal endoglin-targeting antibodies, TRC105, OMTX503 and OMTX703, have demonstrated the decrease in tumor growth in Ewing sarcoma cell line-derived xenografts and patient-derived xenografts as well as in angiosarcoma in clinical trials of Phase I/II." (PMID 32317857, 2020).
leukemia (7 papers, 2013 to 2024). A malignant (clonal) hematologic disorder, involving hematopoietic stem cells and characterized by the presence of primitive or atypical myeloid or lymphoid cells in the bone marrow and the blood. "In order to analyze the role of Endoglin in leukemia cells and their tumor-initiating potential, human blasts from peripheral blood or bone marrow of acute myeloic leukemia (AML) and precursor B-acute lymphoblastic leukemia (ALL) patients were analyzed." (PMID 33287465, 2020). "Early studies led to the identification of Endoglin in the pro-monocytic cell line U937 in addition to the pre-B-leukemia cell line HOON and HUVECs." (PMID 33287465, 2020). "Indeed, human ENG-positive MSCs are strongly correlated with disease progression and poor prognosis in gastric cancer, although this remains controversial since, in some studies, a suppressive effect of MSCs on the growth of leukemia and HCC has also been reported." (PMID 33804796, 2021).
lung adenocarcinoma (7 papers, 2014 to 2022). A carcinoma that arises from the lung and is characterized by the presence of malignant glandular epithelial cells. "Here, we delineated for the very first time the molecular mechanism by which RSVL enhances chemosensitivity and the critical role of ENG in GEM-treated human lung adenocarcinoma cell line HCC827." (PMID 32326402, 2020). "Thus, the drug target potential of ENG for lung adenocarcinoma deserves further studies." (PMID 28178989, 2017). "We found that TGFB1, ENG, TGM2, TBXA2R, HSPG2, and PTPRS were significantly upregulated in lung adenocarcinoma cells." (PMID 36249427, 2022). "Gene expression analysis revealed that four of the five genes, HOXA9, TAL1, ATP8A2, ENG and SPARCL1, each harboring one of the five frequently hypermethylated CpG sites within its promoters, were also frequently down-regulated in lung adenocarcinoma." (PMID 28178989, 2017). "Especially, we found three genes (SPARCL1, ENG and TAL1) harboring frequently hypermethylated CpG sites within their promoters were also frequently down-regulated in lung adenocarcinoma." (PMID 28178989, 2017). "Accordingly, we found five genes (HOXA9, TAL1, ATP8A2, ENG and SPARCL1) corresponding to the five CpG sites had above 90% hypermethylation frequencies in the 539 lung adenocarcinoma samples from TCGA." (PMID 28178989, 2017). "Specifically, we find that INHA and ENG are robust predictors of poor survival in lung adenocarcinomas but not in squamous cell carcinomas." (PMID 33819300, 2021).
squamous cell carcinoma (7 papers, 2014 to 2023). A carcinoma arising from squamous epithelial cells. "Endoglin-positive endothelial cells were found in the neo-vessels of the oral cavity squamous cell carcinomas (SCC) with extensive remodeling and in immature SCC neo-vessels." (PMID 36844233, 2023). "Therefore, we wanted to analyze endoglin expression in three squamous cell carcinoma types: HNSCC, ESCC, and VSCC." (PMID 37396898, 2023). "Squamous cell carcinoma cell lines derived from these SCCs showed variable expression of endoglin." (PMID 37396898, 2023). "The expression of endoglin was also predictive of aggressive biologic behavior of non-melanoma skin cancers – basal and squamous cell carcinomas located mainly in the head and neck region." (PMID 36844233, 2023). "However, when we performed the survival analysis based on different cancer histology, we found that the ENG expression specifically had a strong impact on the survival of patients with adenocarcinoma but not those with squamous cell carcinoma." (PMID 32326402, 2020).
brain arteriovenous malformations (6 papers, 2016 to 2024). "Genetic testing revealed that she and her three daughters carried heterozygous variant of ENG c.1195-1196del p.Arg399GlyfsTer2, which is characterized by pulmonary and cerebral arteriovenous malformations." (PMID 36440054, 2022). "ENG deficiency also impairs the regulation of vascular tone, which contributes to the pathogenesis of brain arteriovenous malformation (bAVM) and vasospasm." (PMID 29098173, 2017). "Increased soluble endoglin (sENG) has been observed in human brain arteriovenous malformations (bAVMs)." (PMID 35163148, 2022). "One study with the endoglin rs10987759 polymorphism shows a trend toward association with sporadic brain arteriovenous malformations, although it does not reach statistical significance." (PMID 32523017, 2020).
myelodysplastic syndrome (6 papers, 2010 to 2023). A clonal hematopoietic disorder characterized by dysplasia and ineffective hematopoiesis in one or more of the hematopoietic cell lines. "The functional mechanisms involved in angiogenesis and the potential role of endoglin (ENG), recently described as a new marker for this process, have not been explored in Myelodysplastic Syndromes (MDS)." (PMID 23341958, 2013).
renal fibrosis (6 papers, 2014 to 2022). A final common manifestation of a wide variety of chronic kidney diseases characterized by glomerulosclerosis and tubulointerstitial fibrosis. "Furthermore, in vivo L-Endoglin overexpression potentiates Smad1 and Smad3 pathways and this effect is associated with higher renal fibrosis development." (PMID 25313562, 2014). "Accordingly, endoglin haploinsufficient mice have reduced radiation-induced renal fibrosis, as well as reduced numbers of myofibroblasts compared to wild-type mice." (PMID 36614087, 2022). "The importance of endoglin in renal fibrosis was documented in several animal models of renal fibrosis." (PMID 34768419, 2021). "Overexpression of endoglin was shown in renal fibrosis models and in various human diseases, including CKD and DN." (PMID 34768419, 2021). "We also suggest that endoglin plays an important role in renal fibrosis by promoting TGF-β-induced fibroblast-to-myofibroblast differentiation and ECM production." (PMID 33081058, 2020). "We found an inverse correlation between interstitial endoglin levels and renal function in patients with DN, which further supports the potential role of endoglin in renal fibrosis in DN." (PMID 33081058, 2020). "Accordingly, compared to wild-type mice, endoglin haploinsufficient mice have reduced radiation-induced renal fibrosis, as well as reduced numbers of myofibroblasts." (PMID 33081058, 2020). "Taken together, the majority of animal studies suggest that endoglin promotes the development of renal fibrosis." (PMID 33081058, 2020). "In previous studies, we have observed that endoglin expression was increased in different experimental models of renal fibrosis." (PMID 25313562, 2014). "It has been also observed that endoglin is overexpressed in several experimental models of renal fibrosis such as renal mass reduction, unilateral ureteral obstruction (UUO) and in radiation-induced fibrosis." (PMID 25313562, 2014). "In this study, our aim has been to evaluate if the overexpression of L-Endoglin, the predominant endoglin isoform, modulates renal fibrosis after UUO." (PMID 25313562, 2014). "In addition, studies in murine models of unilateral ureteral obstruction (UUO)-induced renal fibrosis demonstrated that ENG-overexpressing mice exhibit a higher degree of fibrosis, accompanied by increased collagen and fibronectin." (PMID 35563422, 2022). "Our results support a role for endoglin in developing renal fibrosis in human DN." (PMID 33081058, 2020). "Moreover, endoglin is upregulated in the renal interstitium in several animal models of renal fibrosis, including unilateral ureter obstruction (UUO), ischemia-reperfusion injury, and radiation-induced nephropathy." (PMID 33081058, 2020). "In this study, we investigated whether endoglin also plays a role in the pathogenesis of renal fibrosis in DN." (PMID 33081058, 2020). "The notion that endoglin might play a role in renal fibrosis is supported by findings from several in vivo studies." (PMID 33081058, 2020). "In the kidney, it has been shown that in several animal models of renal fibrosis, including unilateral ureter obstruction (UUO), ischemia-reperfusion injury, and radiation-induced nephropathy, endoglin is upregulated in the renal interstitium." (PMID 36614087, 2022). "The aim of the study was to investigate the predictive value of urinary endoglin, periostin, cytokeratin-18, and transforming growth factor-β1 (TGF-β1) for assessing the severity of renal fibrosis in 81 children with CON and 60 controls." (PMID 34768419, 2021). "It is well-known that TGF-β1 is the major stimulator of endoglin and periostin expression, periostin creates a feedback loop with TGF-β1, and CK18 was identified as an important factor in renal fibrosis." (PMID 34768419, 2021). "In line with the high endoglin expression described in fibrotic tissue, overexpressing endoglin in the UUO model aggravates renal fibrosis." (PMID 33081058, 2020).
renal fibrosis (continued). "Our results suggest that endoglin is an important mediator in the final common pathway of CKD and could be used as a possible new therapeutic target to counteract the development of renal fibrosis and progressive decline of renal function in CKD." (PMID 36614087, 2022). "Therefore, the aim of our study was to investigate the predictive value of urinary endoglin, periostin, CK-18, and TGF-β1 for assessing the severity of renal fibrosis in children with congenital obstructive nephropathy." (PMID 34768419, 2021). "Taken together, these data indicate that endoglin is involved in fibroblast-to-myofibroblast differentiation and promotes TGF-β-induced ECM production, both of which may contribute to the development of renal fibrosis." (PMID 33081058, 2020). "As the expression of the different membrane endoglin isoforms was not assessed in those experiments, and it has been reported that L- and S-Endoglin show distinct modulatory effects on TGF-β signaling, the contribution of endoglin and its isoforms to renal fibrosis remains unclear." (PMID 25313562, 2014).
scleroderma (6 papers, 2013 to 2022). Scleroderma is a rare autoimmune connective tissue disorder characterized by abnormal hardening of the skin and, sometimes, other organs. "Endoglin is strongly expressed in profibrogenic cell types such as mesangial cells, cardiac fibroblasts, scleroderma fibroblasts, and HSCs which are the most fibrogenic cells of the liver." (PMID 31749832, 2019). "The positive effect of endoglin is even more interesting considering that in scleroderma fibroblasts the fibrogenic gene program is mediated via activation of Smad1 and ERK1/2 pathways, which are positively regulated by endoglin." (PMID 23437087, 2013). "Apart from endothelial cells, Endoglin is expressed on a variety of profibrogenic cell populations such as mesangial cells, scleroderma and cardiac fibroblasts and hepatic stellate cells (HSC)." (PMID 23516586, 2013). "Additionally, in patients with scleroderma, endoglin was found to be significantly upregulated in lesional systemic sclerosis fibroblasts." (PMID 36614087, 2022). "Moreover, endoglin upregulation has been reported in fibroblasts in cutaneous skin lesions in patients with scleroderma, in human hepatic stellate cells and in fibroblasts isolated from strictures in Crohn’s disease." (PMID 36614087, 2022). "Other experiments outlined a profibrogenic role of endoglin in HSC cell lines or in scleroderma patient fibroblasts." (PMID 31749832, 2019).
systemic sclerosis (6 papers, 2010 to 2022). A chronic disorder, possibly autoimmune, marked by excessive production of collagen which results in hardening and thickening of body tissues. "Our systematic review is, to date, the first one that specifically aims to discuss the relation between a type III TGFβ receptor, Endoglin, and Systemic Sclerosis." (PMID 36059817, 2022). "This systematic review was designed to highlight the clinical and molecular role of Endoglin in a rare connective tissue disease whose pathogenesis is only partially known, Systemic Sclerosis." (PMID 36059817, 2022). "Serum endoglin levels in patients suffering from systemic sclerosis and elevated systolic pulmonary arterial pressure." (PMID 36059817, 2022).
type 2 diabetes (6 papers, 2010 to 2024). "Sol-endoglin plasma levels are different in patient groups depending on the circadian blood pressure pattern, and increased endoglin levels are associated with retinopathy, very high 10-year cardiovascular risk and increased number of damaged target organs in patients with type 2 diabetes." (PMID 21171985, 2010).
HELLP syndrome (5 papers, 2014 to 2025). A life-threatening condition that can potentially complicate pregnancy. "Soluble fms-like tyrosine kinase-1 (sFlt-1) and soluble endoglin (sEng) are anti-angiogenic proteins associated with preeclampsia and HELLP syndrome whose levels have been found to directly correlate with disease severity." (PMID 32972452, 2020). "Excessive sFlt1 together with lack of eNOS is not sufficient to cause hemolysis, and overexpression of both sFlt1 and soluble endoglin is likely necessary for hemolysis to cause HELLP syndrome." (PMID 29311569, 2018). "Soluble endoglin (sCD105) overexpression is linked to typical systemic and vascular inflammation states such as pre-eclampsia and HELLP syndrome." (PMID 24651155, 2014). "Another molecule, soluble endoglin (sEng), a shed form of the TGF-β co-receptor, rises in severe cases, particularly in PE associated with HELLP syndrome, amplifying endothelial injury by interfering with TGF-β-mediated vascular protection." (PMID 40981151, 2025). "On gestational day (GD) 12, mini-osmotic pumps were inserted into a subset of normal pregnant (NP) rats infusing 4.7 μg/kg soluble fms-like tyrosine kinase-1 (sFlt-1) and 7 μg/kg soluble endoglin (sEng) to induce HELLP syndrome." (PMID 32972452, 2020). "Overexpression of both sFlt1 and soluble endoglin displays the phenotype of HELLP syndrome including hemolysis." (PMID 29311569, 2018).
ischemia (5 papers, 2017 to 2023). A hypoperfusion of the BLOOD through an organ or tissue caused by a PATHOLOGIC CONSTRICTION or obstruction of its BLOOD VESSELS, or an absence of BLOOD CIRCULATION. "In the murine hindlimb ischemia model, the right femoral artery was ligated and excised to mimic peripheral artery disease and image disease-related angiogenesis based on endoglin expression." (PMID 33946583, 2021). "In summary, we give translational evidence that the sequence of hypoxia and subsequent reoxygenation triggers the release of vasoactive soluble endoglin in large-vessel occlusion stroke and can serve as a biomarker for severe ischemia with ensuing recanalization/reperfusion." (PMID 36672223, 2023). "Soluble endoglin significantly decreased the levels of VCAM and E-selectin mRNA expression compared to the WT ischemia group." (PMID 29145462, 2017).
liver disease (5 papers, 2013 to 2026). "We assessed BMP9, BMP10 and soluble endoglin (sEng) levels and their relationships to liver disease severity and associated pulmonary vascular syndromes in a cohort of well-characterised liver disease patients." (PMID 32454407, 2020). "In this report, we observed a significantly increased Endoglin expression in cystic fibrosis associated liver disease." (PMID 23516586, 2013). "TRC105 (carotuximab) is an antibody against endoglin, and three of its clinical trials were related to liver diseases." (PMID 33809908, 2021). "First reports evaluated circulating Endoglin levels in patients with liver disease of diverse etiologies." (PMID 23516586, 2013). "CF Patients with CFLD diagnosed according to recent guidelines exhibited significantly increased serum levels of TIMP-4 and Endoglin compared to those without liver disease." (PMID 23516586, 2013). "Using this approach, our results identify TIMP-4 and Endoglin as novel and promising serum markers of liver disease in CF patients that hold the potential to facilitate the non-invasive assessment of CFLD." (PMID 23516586, 2013).
myeloma (5 papers, 2016 to 2023). "In myeloma patients, diverse angiogenic factors such as VEGF, endoglin, TNF-alpha, HGF, FGF, endostatin, thrombospondin-1 (TSP-1), and angiostatin factor are already well studied in peripheral blood and bone marrow." (PMID 28727816, 2017). "Endothelial cells (ECs) isolated from the bone marrow of multiple myeloma patients (MMECs) express EC markers, including Tie2, vascular endothelial growth factor receptor-2 (VEGFR-2), fibroblast growth factor receptor-2 (FGFR-2), CD105-endoglin and vascular endothelial (VE)-cadherin." (PMID 26919105, 2016).
neuroblastoma (5 papers, 2016 to 2025). Neuroblastoma (NB) is the most common solid, extracranial childhood tumor. "To map the expression of EPAS1 in neuroblastoma in situ, we performed RNA-scope with probes for EPAS1, TH, and the endothelial marker ENG (Endoglin) in tumors of different stages." (PMID 41118218, 2025). "TRC-105, a monoclonal antibody against endoglin (CD105) present on the surface of ECs, CAFs and MSCs, enhances immunotherapy with NK cells in xenotransplanted human neuroblastoma tumors." (PMID 33114328, 2020).
acute lymphoblastic leukaemia (4 papers, 2014 to 2022). "Endoglin was identified as a cell-surface glycoprotein in an acute lymphoblastic leukaemia cell line, and later it was demonstrated to be an accessory receptor for transforming growth factor-β (TGF-β)." (PMID 24949082, 2014).
acute myeloid leukemia (4 papers, 2020 to 2024). Acute myeloid leukemia (AML) is a group of neoplasms arising from precursor cells committed to the myeloid cell-line differentiation. "In cancer, endoglin is highly expressed by acute myeloid leukemia (AML) subsets." (PMID 32059544, 2020).